ZFP14 (ZFP14 zinc finger protein)
Description:
May be involved in transcriptional regulation.
Synonyms: KIAA1559; ZNF531
Tractability: PROTAC: ubiquitination databases record sites on it.
Gene: Protein-coding gene on chromosome 19 (36,334,453 to 36,379,201, reverse strand). Ensembl gene ENSG00000142065.
Subcellular location: Nucleus
Subcellular location (Human Protein Atlas): Nuclear speckles
Pathways (Reactome):
Gene expression (Transcription): Generic Transcription Pathway
Gene Ontology:
Molecular function: protein binding; DNA-binding transcription factor activity, RNA polymerase II-specific; RNA polymerase II cis-regulatory region sequence-specific DNA binding; sequence-specific double-stranded DNA binding
Biological process: regulation of transcription by RNA polymerase II; regulation of DNA-templated transcription
Cellular component: nucleus
Genetic constraint (gnomAD): Loss-of-function variants: 20 observed, 55.41 expected, observed/expected ratio (o/e) 0.36, 90% interval 0.25 to 0.52. The synonymous counts are far from expectation, so gnomAD's model fits this gene poorly and the ratio says little. Missense variants: 470 observed, 671.32 expected, observed/expected ratio (o/e) 0.7, 90% interval 0.65 to 0.76. Synonymous variants: 159 observed, 215.78 expected, observed/expected ratio (o/e) 0.74, 90% interval 0.65 to 0.84.
Homologues: Orthologues: macaque ZFP14 (99% identical), pig ZFP14 (95% identical), guinea pig ZFP14 (93% identical), rabbit ZFP14 (93% identical), mouse Zfp14 (82% identical), rat Zfp14 (80% identical), chimpanzee ZFP14 (15% identical). Paralogues in human: ZFP82 (70% identical), ZFP30 (69% identical), ZNF546 (58% identical), ZNF540 (58% identical), ZNF571 (55% identical), ZNF461 (55% identical), ZNF780B (53% identical), ZNF30 (53% identical), ZNF573 (52% identical), ZNF565 (50% identical), ZNF658 (49% identical), ZNF841 (49% identical), and 164 more.
Diseases named in the same sentence as ZFP14 in open-access papers:
ZFP14 is named in the same sentence as 6 diseases in open-access papers, as found by Europe PMC text mining. Sharing a sentence is not in itself a finding about the gene and the disease. The quoted sentences say what the papers report.
breast carcinoma (2 papers, 2017 to 2025). "Although rarely reported, ZFP14 has been shown to stimulate the in vitro proliferation and migration of colorectal and breast cancer cells, but its role in ccRCC remains unexplored." (PMID 39936533, 2025). "The remaining four CNVRs overlapped with genes ZFP14, JAK1, LPA, PDGFRA and were also associated with RFS in breast cancer." (PMID 29116104, 2017).
tumor (2 papers, 2022 to 2025). "Initially, in mice that underwent subcutaneous injection of these cells, over‐expression of ZFP14 resulted in lower tumour volumes and weights, while deficiency of METTL14 produced an opposite effect which was reversed by augmenting ZFP14." (PMID 39936533, 2025). "In this research, we identified ZFP14 as a tumour suppressor in ccRCC, characterised by its reduced expression, suggesting its potential as a new diagnostic biomarker." (PMID 39936533, 2025). "In summary, these findings identify ZFP14 as not only a tumour‐suppressor in ccRCC but also an important participant for METTL14 to inhibit ccRCC progression." (PMID 39936533, 2025). "In this study, ZFP14 was identified for the first time not only as a tumour suppressor in ccRCC but also as a crucial target of METTL14‐mediated m6A, with IGF2BP2 participating." (PMID 39936533, 2025). "Our bioinformatic analyses indicated a potential tumour‐suppressing role for ZFP14 in ccRCC, suggested by the positive correlation between its low expression, tumour progression and poor patient prognosis." (PMID 39936533, 2025). "Our research indicated that ZFP14 functioned as a tumour suppressor in ccRCC by promoting the ubiquitination of signal transducer and activator of transcription 3 (STAT3), an established oncogene implicated in multiple cancers, including ccRCC." (PMID 39936533, 2025). "Additionally, ZFP14 expression decreased with increasing tumour stage, pathological grade and the presence of lymph node metastasis." (PMID 39936533, 2025). "This further indicated ZFP14’ as a tumour suppressor in ccRCC." (PMID 39936533, 2025). "Based on these findings, we considered ZFP14 a potential tumour suppressor in ccRCC." (PMID 39936533, 2025). "ZFP14 levels were assessed in the transplanted tumours by western blot assay." (PMID 39936533, 2025). "Additionally, ZFP14 mitigated the STAT3‐enhanced tumour metastasis." (PMID 39936533, 2025). "We sought to explore the biological functions of ZFP14 in ccRCC, particularly its role in METTL14's tumour‐suppressing effects, as previously demonstrated." (PMID 39936533, 2025). "Additionally, total m6A richness in the tumours was positively correlated with the expressions of METTL14 and ZFP14." (PMID 39936533, 2025). "However, the under‐expression of ZFP14 in tumour tissues was not statistically significant, likely due to comparisons with non‐paired normal tissues in the TCGA cohort." (PMID 39936533, 2025).
cancer (1 paper, 2022). A tumor composed of atypical neoplastic, often pleomorphic cells that invade other tissues. "To determine the function of ZFP14 in mouse and human cancer cell lines, we generated multiple cell lines where ZFP14 was knocked out." (PMID 36358645, 2022). "We showed that ZFP14-KO inhibits cancer cell growth and migration." (PMID 36358645, 2022). "To test this, we transiently expressed mouse/human ZFP14 in multiple mouse and human cancer cells." (PMID 36358645, 2022). "The biological functions of most KRAB-ZFPs are unknown and thus the identification of the physiological and cancer-specific function of ZFP14 is significant." (PMID 36358645, 2022). "Furthermore, scratch assays showed decreased cell migration in ZFP14-KO clones compared to the isogenic control cells in both HCT116 and MCF7 cells, suggesting that ZFP14 promotes cancer cell proliferation and migration." (PMID 36358645, 2022).
ZFP14 also shares sentences with these, for which no sentence is quoted: asthma (1 paper); clear cell renal cell carcinoma (1); prostate carcinoma (1).